RAD54B (RAD54 homolog B)
Diseases named in the same sentence as RAD54B in open-access papers (continued):
Sharing a sentence is not in itself a finding about the gene and the disease.
cancer (21 papers, 2009 to 2025). A tumor composed of atypical neoplastic, often pleomorphic cells that invade other tissues. "Collectively, these data suggest diminished RAD54B expression and/or function are pathogenic events in the development and progression of cancer." (PMID 27902462, 2016). "In a CRC context, a synthetic lethal (SL) approach aims to exploit a pre-existing gene deletion or mutation (e.g. RAD54B) in a cancer cell by down regulating a SL interactor (i.e. drug target)." (PMID 27902462, 2016). "Postoperative recurrence risk stratification by RAD54B expression will be beneficial for more individual cancer strategies." (PMID 26046797, 2015). "Consistent with this thought, cancer tissues harboring RAD54B mutations contain more DSBs." (PMID 35952757, 2022). "Various studies have revealed that Rad54B mutation is involved in the development of some cancer’s cells, and such abnormal proteins are unable to terminate the cell cycle and will lead to the progression of cancer." (PMID 34198769, 2021). "Furthermore, somatic mutations of SOD1 are rare in cancer, and those few that do occur are mutually exclusive of those occurring for RAD54B, BLM and CHEK2." (PMID 26318585, 2015). "RAD54B displays oncogene-like characteristics and is amplified or overexpressed in a diverse array of cancer types, including colorectal, lung, prostate and breast." (PMID 40290304, 2025). "RAD54B has been considered a key player in HR repair, although its roles and therapeutic potential in cancers need further investigation." (PMID 35952757, 2022). "Second, the pathogenicity of several cancer-associated genetic variants, including PRSS1 c.161A > G, SLC22A18 c.257G > A, and RAD54B c.1778A > G, was misclassified." (PMID 30850667, 2019). "For example, PARP inhibitors that target BRCA1/2 defects underlying HRR-deficiencies are also effective at killing cancer cells harboring defects in additional HRR genes, like RAD51, ATM, ATR, CHEK1, and RAD54B." (PMID 29104272, 2017). "The present study focuses on RAD54B, a gene that is aberrantly expressed in many cancer types, including CRC." (PMID 27902462, 2016). "This suggests that inhibition of F2 (for example RAD54/RAD54B) would be particularly effective to sensitize cancer cells overexpressing F1 components (e.g. RAD51 paralogs, RAD51, RAD52, BRAC2), a non-intuitive insight derived from the mathematical modeling." (PMID 23592964, 2013). "Besides, the pan-cancer analysis revealed that RAD54B expression was also prominently enhanced in the majority of cancers, including STAD." (PMID 38378037, 2024). "In addition, multiple new SL interactions were recently identified in pre-clinical studies involving various CIN genes altered in cancers, such as RAD54B, CHEK2, BLM, PTEN, and TDP1." (PMID 29104272, 2017). "For example, RAD54B is somatically mutated or deleted in numerous cancer types, including CRC (∼3.3%), breast (∼3.4%), lung (∼2.6%), which represents ∼20,500 North Americans each year who are newly diagnosed with these three cancers alone." (PMID 27902462, 2016). "Thus dysregulated, unscheduled and unnecessary recombination events and loss of checkpoint controls (whether mediated by drivers of genomic instability such as RAD54B and/or other mechanisms) are attributed to genomic instability in cancer." (PMID 36428789, 2022). "In addition to RAD54B, we also analyzed RAD51 expression in the same cohort because RAD51 is another important factor involved in HR process and several studies reported that RAD51 protein overexpression is associated with poor prognosis in various cancers." (PMID 26046797, 2015).
cancer (continued). "Gain of MRN complex genes, RAD54B and RAD51B, whose alterations were reported to be involved in cancer progression, was related to poorer overall survival." (PMID 33178606, 2020). "RAD54B has been investigated as a predictive marker for HCC patients, and it may play a significant role in the development of HCC through cancer cell DNA amplification." (PMID 37923899, 2023). "Notably, mammalian SOD1 has been explored as a cancer therapeutic target for the selective killing of cancer cells with defective HR genes, such as BLM or RAD54B." (PMID 37638880, 2023).
tumor (20 papers, 2013 to 2025). "We determined that RAD54B-mutated tumor tissues harbored more DNA double-strand breaks than normal tissues." (PMID 35952757, 2022). "Relative to control cells, the suppression of all three genes (TTK, TPX2, and RAD54B) was associated with significant reduction in tumor size (p ≤ 0.04) in SCID mice." (PMID 34031527, 2021). "RAD54B is normally involved in homologous recombination repair and somatic mutations are found in numerous tumor types." (PMID 24202319, 2013). "RAD54B detects copy number variations, single nucleotide polymorphisms, and aberrant mRNA expression in multiple tumor types and has been shown to be closely related to tumor prognosis." (PMID 35847584, 2022). "We found that RAD54B was significantly highly expressed in lymphoid tissues, and the high expression of RAD54B in tumor tissues with LNM may be partly due to the contribution of tumor neoplastic lymphatic vessels, which proved to be associated with LNM." (PMID 35847584, 2022). "Overexpression of ATAD2 and PVT1 in 8q24.13, RAD54B, LAPTM4B, and RRS1 in 8q21.13 were reported to be associated with tumor proliferation and progression of HCC." (PMID 36010950, 2022). "Further analysis of TCGA LIHC data using the MEXPRESS platform showed that RAD54B expression in tumor tissue was inversely correlated with age at initial pathologic diagnosis and OS." (PMID 35847584, 2022). "We elucidate the critical role of miR‐215/RAD54B axis in BC, which provides reference value for perfecting the regulatory role of miRNAs in tumours." (PMID 33635591, 2021). "Indepth evaluation of three genes (TTK, TPX2 and RAD54B) confirms their role in genomic instability and tumor growth." (PMID 34031527, 2021). "Rad50, Rad51, Rad54b, Mre11a, Palb2, Brca1 and Bard1 all showed significantly higher expression in resistant tumours compared to responding tumours (p = 0.05, p < 0.001, p < 0.001, p < 0.001, p = 0.002, p < 0.001 and p = 0.012 respectively)." (PMID 31080552, 2019). "Results exhibited that knockdown of RAD54B significantly decreased the tumor volume and weight." (PMID 38378037, 2024). "Moreover, the level of RAD54B was confirmed to be enhanced in the STAD primary tumor samples relative to that in normal samples based on the GEPIA." (PMID 38378037, 2024). "AC012213.3 regulated the RAD54B/PI3K/AKT axis to exert its oncogenic function in tumor cells." (PMID 37596669, 2023). "The Ki67 levels were significantly decreased in RAD54B-knockdowned tumor groups." (PMID 35952757, 2022). "Although the RAD54B high group had more advanced T stage (P = 0.027), factors including sex, age, tumor location, tumor size, cell differentiation, lymphatic invasion, venous invasion, preoperative tumor markers, UICC stage, and N stage were similar in both groups." (PMID 26046797, 2015). "Moreover, AC012213.3 targeted RAD54B, which resulted in tumor progression." (PMID 37596669, 2023). "Drawing from the TCGA-BLCA cohort, we discovered that RAD54B and KPNA2 expressions rose in tumor tissues, whereas TPM1 expressions declined in comparison to corresponding normal tissues." (PMID 38735911, 2024). "In addition, RAD54B was selected by regression model as an independent risk factor affecting the prognosis of HCC patients with LNM, and its expression was significantly positively correlated with tumor mutational burden and microsatellite instability in high-risk subtypes." (PMID 35847584, 2022). "Given that RAD54B interacts with RAD51 and DMC1 to enhance the D-loop formation and DNA-strand exchange during HR, this protein was suggested to be critical in DNA repair and harbored with tumor suppressor–like properties." (PMID 35952757, 2022).
RAD54B also shares sentences with these, for which no sentence is quoted: anemia (3 papers); albinism (1); bladder cancer (1); cholangiocarcinoma (1); glioblastoma (1); hypopharyngeal cancer (1); lung squamous cell carcinoma (1); lymphoma (1); oculocutaneous albinism type 1 (1); severe combined immunodeficiency (1); triple-negative breast carcinoma (1).